IGF2 (insulin like growth factor 2)
Diseases named in the same sentence as IGF2 in open-access papers (continued):
Sharing a sentence is not in itself a finding about the gene and the disease.
Beckwith-Wiedemann syndrome (continued). "In developmental syndromes, such as Beckwith-Wiedemann syndrome, dysregulation of the H19/insulin-like growth factor 2 (IGF2) imprinting control region leads to H19 downregulation and IGF2 overexpression, driving embryonic cell overgrowth and differentiation defects." (PMID 40259926, 2025). "For example, Beckwith-Wiedemann syndrome can result from increased expression of insulin-like growth factor 2 (IGF2), a paracrine growth factor, and/or from decreased expression or inactivating variants in cyclin-dependent kinase inhibitor 1c (CDKN1C), which regulates cell cycle progression." (PMID 36927955, 2023). "DNA methylation abnormalities of the H19/IGF2:IG-DMR cause contrasting growth disorders (i.e., Beckwith-Wiedemann syndrome (BWS, MIM#130650) and Silver-Russell syndrome (SRS, MIM#180860)), if they are present on the maternal or paternal chromosome, respectively." (PMID 29484033, 2018). "Notably, these cloned piglets with macroglossia were accompanied with the high methylation and expression levels of H19/Igf2, similar to Beckwith Wiedemann syndrome in human assisted reproduction." (PMID 25962071, 2015). "There may also be an independent mechanism for regulating IGF2 in Beckwith-Wiedemann syndrome (BWS) patients." (PMID 19737423, 2009). "The human imprinted gene CDKN1C is the most frequently silenced or mutated gene in the imprinting genetic disorder Beckwith-Wiedemann syndrome (BWS); aberrant imprinting of IGF2 has also been shown to interact with CDK1C in this imprinting disorder." (PMID 36633189, 2023). "Accordingly, it has been reported that hypermethylation at H19/IGF2:IG-DMR is present in the premalignant clonal expansions of WTs, representing an early event in Wilms tumorigenesis, and as constitutional epimutation in the Beckwith-Wiedemann syndrome cases with high predisposition to WTs." (PMID 33217932, 2020). "However, a transgenic mouse model for IGF2 (without including the miR-483 gene) exhibited several features associated with the Beckwith-Wiedemann syndrome without association to any neoplasia." (PMID 29867024, 2018). "These functional associations of IGF2 and KCNQ1 rely on publications reporting how a differentially methylated region in KCNQ1 controls imprinted expression of other genes in the neighborhood and about epigenetic abnormalities in the IGF2/H19 region of Beckwith-Wiedemann syndrome patients." (PMID 23226257, 2012). "As an example, patients with Beckwith-Wiedemann Syndrome (BWS), linked to chromosome 11p15.5, have abnormal hypermethylation of the maternal H19 ICR, leading to higher expression of IGF2 with an overgrowth syndrome and increased cancer risk." (PMID 18414667, 2008). "TGF-β, together with the tumor suppressor CTCF, epigenetically and/or transcriptionally regulate tumor promoter genes, including IGF2, TERT, and Myc in TGF-β–defective mice and in patients with Beckwith-Wiedemann syndrome (BWS), a human stem cell disorder." (PMID 33457451, 2020). "For example, Beckwith-Wiedemann Syndrome (BWS) with RMS involves dysregulation or alteration of imprinted genes in the 11p15.5 chromosomal region, including IGF2, H19, and CDKN1C (p57/KIP2)." (PMID 26420980, 2015). "Most notably, both IGF2 and the maternally expressed cell cycle inhibitor CDKN1C can contribute to the overgrowth disorders seen in Beckwith-Wiedemann syndrome and there is evidence that changes in Igf2 expression can influence expression of Cdkn1c." (PMID 25551289, 2014). "In case of Beckwith-Wiedemann syndrome, demethylation of the IGF2/H19 imprinting control region leads to the binding of CTCF and subsequently blocks the connection between an enhancer for IGF2 and promotes activation of maternal H19." (PMID 25340699, 2014). "Beckwith-Wiedemann syndrome (BWS) is a fetal overgrowth and human imprinting disorder resulting from the deregulation of a number of genes, including IGF2 and CDKN1C, in the imprinted gene cluster on chromosome 11p15.5." (PMID 19300480, 2009).
Beckwith-Wiedemann syndrome (continued). "Beckwith-Wiedemann syndrome (BWS, OMIM 130650), either sporadic (>85%) or familial (<15%), is caused by mutation or deletion of imprinted genes CDKN1C, H19 and LIT1 as well as by hypermethylation in the H19/IGF2-imprinting control region within the chromosome 11p15.5 region." (PMID 29190888, 2017).
colon carcinoma (62 papers, 2000 to 2026). "Experimental studies have shown that colon cancer cell lines co-cultured with cancer-associated fibroblasts overexpressing IGF2 demonstrated increased invasiveness." (PMID 39068768, 2024). "Using the GSE89093 dataset, IGF2 hypermethylation was strongly associated with an increased risk of CRC or colon cancer alone." (PMID 37213278, 2023). "Others have reported that hypomethylation of these same CpGs is associated not only with loss of IGF2 imprinting, but also to risk of colon cancer, with hypomethylation detected in 10% of an otherwise unaffected population." (PMID 26343731, 2015). "This is exemplified by the observations that the normally silenced state of the maternally inherited IGF2 allele is lost in several cancer forms, such as Wilms’ tumor and colon cancer, resulting in LOI and an activation of biallelic expression patterns." (PMID 23023303, 2012). "Furthermore, Nakagawa and coworkers demonstrated that methylation-dependent loss of IGF2 imprinting was present in colon tumours and normal colonic mucosa, suggesting that IGF2 overexpression predisposes to cancer." (PMID 27152123, 2016). "It is concluded that this gene therapy vector is effective in the suppression of the growth of human colon cancer cells in vitro and in vivo, and that cancer gene therapy based on loss of IGF2 imprinting may prove to be a novel therapeutic option." (PMID 23900345, 2013). "Moreover, the expression of IGF2 in colon cancer was associated with poor prognosis." (PMID 36672737, 2023). "For example, hsa-miR-185-5p is a tumor suppressor in endometrial cancer and colon cancer, where it promotes migration and invasion by regulating IGF2." (PMID 41200507, 2025). "A significant highlight of this work is our innovative use of GENET to discover and validate a new pathway in colon cancer, specifically, the promotion of IGF2 by WNT4 through the activation of STAT3." (PMID 39373342, 2024). "Traditionally, unraveling the mechanisms involving WNT4 and IGF2 in colon cancer would require extensive literature reviews or costly high‐throughput screening technologies." (PMID 39373342, 2024). "mir185-5p has been found to bind both NEAT1 and IGF2 transcripts, and it upregulates IGF2 while enhancing migration and invasion in colon cancer cells." (PMID 37371750, 2023). "Insulin-like growth factor 2 (IGF2) is the most common cause of LOI due to hypomethylation, and it has been linked to a variety of tumors, including breast, liver, lung, and colon cancer." (PMID 36447689, 2022). "NEAT1 triggered cell proliferation and migration in colon cancer by inhibiting miR-185-5p and elevating IGF2." (PMID 33902591, 2021). "In vitro studies showed 80-fold increases in IGF2 production by tumorigenic clones of the SW613-S human colon carcinoma cell line compared to IGF1." (PMID 31623387, 2019). "In vitro studies also showed that IGF2 can play an important role in cell proliferation as well as differentiation of “normal” colonic cells and CaCo-2 colon carcinoma cell line." (PMID 31623387, 2019). "Quantitative studies show an increased tissue IGF2 expression (mRNA and protein) in a number of colonic cancer cell lines derived from adult tumors as well as in human primary and metastatic colonic carcinoma." (PMID 31623387, 2019). "Increases in tumor invasiveness, dissemination capacity, and local tumor regrowth were noted after inoculation of colon cancer cells with CAFs expressing endogenous IGF2 in mouse xenograft models." (PMID 31623387, 2019). "This specific inhibitor of IGF2 bioavailability, when administered to an IGF2 overexpressing colon cancer mouse model, rescued Igf2-dependent intestinal and adenoma phenotype." (PMID 31623387, 2019). "Loss of imprinting at the insulin-like growth factor 2 (IGF2) gene locus is frequently observed in cancer and is provided as a colon cancer diagnosis." (PMID 30806885, 2019).
colon carcinoma (continued). "People with serum IGF2 levels in the upper quartile of the normal range (and IGFBP3 in the lower quartile) have a higher relative risk for developing cancer, including colon cancer." (PMID 31623387, 2019). "A growth inhibitory effect of ellagic acid (10 μM) has been reported for SW480 colon cancer cells through downregulation of the insulin-like growth factor 2 (IGF-II) signalling pathway." (PMID 28933410, 2016). "The first reports of methylation plasticity of the IGF2 DMR came from studies of individuals with colon cancer." (PMID 26343731, 2015). "In conclusion, an IGF2 imprinting-based gene therapy vector has been developed that is effective in inhibiting the growth of human colon cancer cells in vitro and in vivo." (PMID 23900345, 2013). "Strong inverse associations between DNA methylation levels at the IGF2 DMR using DNA obtained from leukocytes, biallelic expression of this otherwise monoallelically expressed gene, and elevated colon cancer risk have been reported." (PMID 22392079, 2012). "Additional studies have reported a range from 33% to 87% of sporadic colon cancers that were related to LOI of IGF2." (PMID 23171475, 2012). "The finding that IGF2 LOI in peripheral blood cells is the earliest predictive marker for colon cancer reinforces the notion that constitutive epigenetic lesions predispose for cancer." (PMID 23023303, 2012). "Loss of imprinting at this IGF2 DMR has been associated with a higher risk of overgrowth disorders in childhood and colon cancer in adulthood." (PMID 21255390, 2011). "In vitro studies showed the increase in IGF2 production in diverse colon cancer cell lines." (PMID 38542291, 2024). "Secondly, while we have identified and validated a potential mechanism involving WNT4, STAT3, and IGF2 in colon cancer using sequencing data and immunofluorescence techniques, additional technologies such as WB and PCR are required to verify their regulatory relationships." (PMID 39373342, 2024). "The expression of LncRNA NEAT1 is closely related to the overall survival of colon cancer patients, and overexpression of NEAT1 can significantly promote the migration and invasion of colon cancer cells by competitively and endogenously binding to miR-185-5p to regulate IGF2." (PMID 38002356, 2023). "Overexpressed NEAT1 via the miR-185-5p/IGF-2 axis could promote invasion and migration of colon cancer cells." (PMID 33768092, 2021). "Recent studies based on TCGA analysis revealed that, in human colon cancer specimens, a stronger activity of β-catenin/TCF responsive promoter was associated with a higher transcription of IGF2 and IGF1R, which can be important in design of therapies employing IGF1R/IR inhibitors." (PMID 31623387, 2019). "In the TCGA colon cancer study, the IGF2 was amplified and overexpressed." (PMID 28567416, 2017). "Similar mechanism has been described for IGF2 (maternal imprinting) in colon cancer cells." (PMID 28139749, 2017). "Of note, IGF-2 is overexpressed in many solid tumors including colon cancer." (PMID 26504896, 2015). "IGF2 LOI is an aging-related epigenetic event that we postulate may be modulated by inflammation, a common feature associated with prostate and colon cancer development." (PMID 24558376, 2014). "For example, insulin-like growth factor 2 (IGF2) loss of imprinting, which places individuals at increased risk of developing colon cancer, is not caused by exposure to adult environmental factors." (PMID 16581547, 2006). "Similarly, the Igf2 mRNA-binding protein 1 (IMP-1), another RBP protein, has been shown to induce loss in epithelial characteristics and acquisition of “stem-like” phenotype when overexpressed in colon cancer cells." (PMID 32759946, 2020). "Moreover, IGFBP-6 expression has been previously associated with nonproliferative states and inhibition of IGF-2 dependent tumor cell growth in rhabdomyosarcoma, neuroblastoma, and colon cancer." (PMID 29387091, 2017).
colon carcinoma (continued). "Pearson correlation analysis of transcriptome data from 14 patients with colon cancer indicated strong positive correlations between WNT4 and STAT3, and between STAT3 and IGF2." (PMID 39373342, 2024). "Highly connected biomarkers (with degree centrality) were BRAF mutation (0.19) and methylation-related markers including CDKN2A (0.17), IGF2 (0.17), RUNX3 (0.17), CACNA1G (0.15), CRABP1 (0.15), and NEUROG1 (0.15) in the proximal colon cancer network." (PMID 28623901, 2017). "In total, 31 CpG sites, located in 8 different genes (RUNX3, MLH1, NEUROG1, CDKN2A, IGF2, CRABP1, SOCS1 and CACNA1G) were investigated in 64 distinct colon cancers and 2 colon cancer cell lines." (PMID 24466191, 2014). "Additionally, multiplex immunofluorescence analyses of pathological sections from 25 patients with colon cancer confirmed co‐expression of WNT4, STAT3, and IGF2." (PMID 39373342, 2024). "Our study suggests that for the diagnosis of colon cancer, it is better to examine the expression status rather than the methylation status of IGF2, SOCS1, MLH1, and CACNA1G genes." (PMID 38874740, 2024). "Moreover, the NEAT1/miR-185-5p/insulin-like growth factor 2 (IGF2) axis is another pathway that induces the invasion and migration of colon cancer." (PMID 34512157, 2021). "IGF2 similarly to IGF1 co-activates proliferative and apoptotic pathways in LIM 1215 colon cancer cells, which may contribute to increased cell turnover." (PMID 31623387, 2019). "This phenomenon can, however, not explain the appearance of LOI of IGF2 in correlation with hypomethylation at the maternal ICR which has been reported in colon cancer and bladder cancer." (PMID 23023303, 2012). "Tumor tissue extracted from 48 colon cancer patients significantly overexpressed IGF-1R and IGF-2 mRNA, but not IGF-1 mRNA." (PMID 22159423, 2012).
lung cancer (60 papers, 2005 to 2026). A malignant neoplasm involving the lung. "Transgenic animals over-expressing IGF2 have been shown to be at increased risk of developing mammary gland adenocarcinoma and lung cancer." (PMID 32703985, 2020). "In lung cancer, loss of imprinting of the IGF2 gene has also been reported as a growth-promoting alteration in lung adenocarcinoma." (PMID 32726996, 2020). "Previous studies have shown that elevated IGF2 level is associated with a reduced survival rate in lung cancer." (PMID 31245293, 2019). "IGF2 secreted by cancer cells promotes cancer progression, and cancer-associated fibroblasts and IGF2 regulate the plasticity of lung cancer stemness via paracrine signaling." (PMID 30013477, 2018). "The loss of imprinting of IGF2 and H19 from parental alleles were previously linked to cervical cancer; Loss of imprinting of H19 was also linked to lung cancer and hepatoblastoma." (PMID 28198667, 2017). "In the present study, loss LOI of IGF2 in lung cancer was analyzed using polymerase chain reaction-restriction fragment length polymorphism (PCR-RFLP) in combination with DNA sequencing of samples collected by laser capture microdissection." (PMID 25364428, 2014). "Aberrant IGF2 expression is associated with diseases like breast, colon, and lung cancers." (PMID 39545420, 2024). "It has recently been hypothesized that ZFP57 is a potential susceptibility gene for lung cancer development through the increase of IGF2 expression." (PMID 34262872, 2021). "This metabolic shift increases IGF2 secretion, which induces PD-L1 expression on lung cancer cells via the IGF2–IR pathway to suppress T cell responses, resultantly facilitating tumor progression." (PMID 41557725, 2026). "Our finding provides a new insight for lung cancer therapy by targeting IGF2-mediated autophagy induction." (PMID 39759028, 2024). "In the present study, we found that lung cancer cells activated NFs to CAFs via autophagy induction, and IGF2-secreted by lung cancer cells mediated the autophagy induction of NFs." (PMID 39759028, 2024). "Our study revealed the critical role of IGF2-mediated autophagy in the activation of CAFs, more importantly, the interplay between lung cancer cells and stromal fibroblasts in the TME, and identified IGF2 as a candidate target for lung cancer treatment." (PMID 39759028, 2024). "In our study, we found that lung cancer cells reprogramed NFs into CAFs through IGF2 secretion, demonstrated by applying recombinant IGF2, IGF2 neutralizing antibody, and IGF2 knockdown." (PMID 39759028, 2024). "Moderate NB exposure induced IGF2 expression in AT2s during the development of pulmonary emphysema and lung cancer in mice." (PMID 38902841, 2024). "Collectively, our data provided the first evidence that lung cancer cells activated NFs to iCAFs via IGF2 secretion." (PMID 39759028, 2024). "As expected, IGF2 knockdown in lung cancer cells mitigated the promoting effect of lung cancer cell-CM on CAFs markers expression and cell migration." (PMID 39759028, 2024). "Since we found that lung cancer cells possessed higher level of IGF2 than NFs, this implied the possibility that lung cancer cells reprogram NFs via IGF2 secretion." (PMID 39759028, 2024). "Altogether, our results indicated that IGF2-induced autophagy mediated the effect of lung cancer cells on CAFs activation." (PMID 39759028, 2024). "In this study, we demonstrated that lung cancer cells activated CAFs via IGF2-mediated autophagy induction; in return, activated CAFs stimulated lung cancer cell migration and invasion via CXCL12-mediated AKT/NF-κB pathway." (PMID 39759028, 2024). "One circulating tumor cell NGS assay in early-stage lung cancer patients showed that more than 50% of lung cancer patients presented four common mutations, including Notch1, EGFR, IGF2, and PTCH1." (PMID 36874015, 2023).